E2F8 (E2F transcription factor 8)
Diseases named in the same sentence as E2F8 in open-access papers (continued):
Sharing a sentence is not in itself a finding about the gene and the disease.
tumor (continued). "The expression profile of E2F8 was then further validated by qRT-PCR in 64 paired PTC patients’ tissues (tumor and adjacent normal tissues)." (PMID 28270228, 2017). "The E2F8-overexpressing tumors grew at a much higher rate in terms of size and weight, than the control tumors, whereas the tumors formed by E2F8-silenced cells were smaller and had lower tumor weights than the tumors formed from shRNA-vector control cells." (PMID 26992224, 2016). "Interestingly expression was detected mainly in the cytoplasm (E2F1) and both cytoplasm and nucleus (E2F8) of tumor cells." (PMID 38686617, 2024). "However, some E2Fs act as tumor suppressors, including E2F8, a gene included in the Magenta_IS score." (PMID 36575316, 2023). "This suggests that DBP and E2F8 in Th9 cells may function through regulation of Granzyme B for their anti-tumor function." (PMID 36241625, 2022). "E2F8 is also a critical tumor suppressor for postnatal liver development." (PMID 35371973, 2022). "Moreover, the results from a correlation expression analysis and latter ChIP-PCR suggested E2F8 as a key candidate for CHEK1 transcriptional activity regulation in GBM tumor cells." (PMID 35409080, 2022). "Finally and significantly, the opposing regulatory roles between DBP and E2F8 in Th9 cells contribute to Th9-mediated anti-tumor immunity in tumor in vivo and also play an important role in human TH9 differentiation." (PMID 36241625, 2022). "Notably, Th9 cells with siRNA-mediated knockdown for Dbp or E2f8 promote and suppress tumor growth, respectively, in mouse tumor models." (PMID 36241625, 2022). "Furthermore, the tumors originating from the E2F8-knockdown A2780 cells showed a significantly reduced tumor size, compared to that of the control tumors." (PMID 32823614, 2020). "Our research further demonstrated that E2F8 expression was significantly correlated with that of the EMT and Notch signaling pathway-related markers, indicating that E2F8 is among the factors influencing tumor progression through the EMT and Notch signaling pathways." (PMID 32823614, 2020). "In addition, atypical E2F8 showed suppress effects on tumor angiogenesis in three different cancer models." (PMID 31990034, 2020). "Conclusively, up-regulated in tumors, E2F8 might accelerate tumor progression and result in unfavorable outcomes in HCC patients." (PMID 31990034, 2020). "To explore whether E2F8 affected tumor growth in vivo, we implanted HeLa and ME180 cells, in which E2F8 was knocked down, as xenografts into nude mice." (PMID 31929759, 2020). "E2F8 is also upregulated in LC, and si-E2F8 significantly represses tumor growth in vivo." (PMID 29754146, 2018). "E2F8 was found to be markedly overexpressed in HCC to facilitate tumor occurrence and development via activation of an E2F1/cyclin D1 signaling pathway to regulate the G1- to S-phase transition of cell cycle progression or transcriptionally suppress CDK1 to induce hepatocyte polyploidization." (PMID 30326936, 2018). "Our results suggest that the miR-144/E2F8/CCND1 axis might function as a key pathway regulating tumor cell proliferation during PTC development." (PMID 28270228, 2017). "Herein, we found that E2F8 was further elevated in luminal B, basal-like and Her2-enriched subtypes than luminal A. E2F8 expression levels positively correlated with the proliferation marker Ki67 in patient tissues and in vivo tumor models." (PMID 26992224, 2016). "However, measurements of motif activity correlation with mRNA expression of the TFs shows that the expression of E2F1, E2F2 and E2F8 exhibit the most significant correlation with E2F motif activity in the time course and tumor studies." (PMID 24464994, 2014). "Ectopic over-expression of E2F8 promoted cell proliferation, colony formation and tumorigenicity, whereas the E2F8 knockdown inhibited these phenotypes suggesting that the down-regulation of E2F8 induced by Bozepinib could contribute to its anti-tumor effect." (PMID 24946763, 2014).
tumor (continued). "Therefore, targeting E2F8 may present a promising therapeutic approach to disrupt cancer stem cells and hinder tumor growth and progression." (PMID 39061176, 2024). "However, other studies also identify E2F8 as a tumor suppressor." (PMID 36814821, 2023). "To explore the cell type specifically of these genes in tumour and normal samples, we analysed their expression in endothelial cells and macrophages and found low expression of E2F8 in normal epithelial cells, which may indicate that its presence promotes cancer." (PMID 33499863, 2021). "Moreover, the E2F7 and E2F8 expressions were positively related to tumor purity in GBM remarkably." (PMID 33381564, 2020). "Moreover, miR-144 appears to be a tumor suppressor through direct inhibition of E2F8." (PMID 28270228, 2017). "Importantly, E2F1, E2F2 and E2F8, previously identified as strong candidate regulators of early PB-mediated transient hyperplastic response, display similar positive correlation between their gene expression and the motif activity in the tumor." (PMID 24464994, 2014). "E2F8, WDR77, and hsa-miR-495-3p stood out as biological features, while pathological stage, age, new tumor event, lymph node count, and chemotherapy have shown themselves as interesting clinical features." (PMID 41401030, 2025). "In this study, we too observed remarkably high similarity of E2F8 and HEC1 in tumor cell distribution." (PMID 39021287, 2024). "E2F8 is a transcription repressor that antagonizes E2F1 in regulating the cell cycle, apoptosis, and tumor promotion." (PMID 36499314, 2022). "The TFs for cycling tumor cells mainly regulate the expression of genes required for progression through the cell cycle (e.g., BRCA1, E2F8), consistent with its proliferation phenotype." (PMID 35860547, 2022). "Having established opposing functions for DBP and E2F8 in Th9 cell differentiation in vitro, we next determined the roles of DBP and E2F8 in Th9 cell-mediated anti-tumor activity in vivo." (PMID 36241625, 2022). "Consistently, our results also indicated that E2F8 was up-regulated in HCC tumors and correlated with advanced tumor stage and AFP elevation." (PMID 31990034, 2020). "Given the better performance of E2F7 and E2F8 in predicting patient outcome, we further explored the oncogenic role of E2F7 and E2F8 in HGG tumor cells." (PMID 32064771, 2020). "Among these features, seven were clinical: pathological stage, new tumor event, age, number of lymph nodes, chemotherapy, number of positive lymph nodes, and ethnicity; and four were biological features: hsa-miR-495-3p, WDR77, E2F8, and APCDD1." (PMID 41401030, 2025). "WPMY-1 cells, while sharing some TFs, showed higher activity of TFs associated with cell cycle regulation and proliferation, such as E2F family members (E2F1, E2F4, E2F8) and JUN, highlighting key regulatory differences between tumor-derived CAFs and benign stromal fibroblasts." (PMID 41198614, 2025). "Therefore, E2F8 possibly affects HEC1‐mediated DNA replication and repair in tumor cells through the regulation of HEC1 expression." (PMID 39021287, 2024). "It is speculated that E2F8 is upregulated in TNBC, which affects the proliferation and development of MKI67+ progenitor cells and tumor cells, as well as the poor prognosis of patients." (PMID 37686305, 2023). "For some genes, such as Klf7, both H3K4me1 and H3K27ac increased on the AP-1 enhancers in tumor tissues; for others, such as E2f8, H3K4me1 did not change obviously while H3K27ac significantly increased." (PMID 34409068, 2021). "In TCGA dataset, heatmap of E2F8 expression in 50 paired tumor and nontumor tissues was calculated, indicating that E2F8 was up-regulated in HCC tumors." (PMID 31990034, 2020). "Consistently, E2F8 mRNA was significantly up-regulated in tumor tissues than nontumors in 6 GEO series including GSE45436, GSE55092, GSE60502, GSE84402, GSE33006 and GSE74656 (all P < 0.01)." (PMID 31990034, 2020).
tumor (continued). "In addition, we found E2F7 and E2F8 demonstrated much higher correlation with VIM, a crucial epithelial‐mesenchymal transition (EMT) marker in tumor cells." (PMID 32064771, 2020). "Remarkably, E2F8 was reported to promote the transcriptional activation of VEGFA via hypoxia-inducible factor 1 while suppressing the transcription of VEGFR1/2 in endothelial cells during embryonic and tumor development." (PMID 32823614, 2020). "We found that E2F8 was significantly up-regulated in tumor tissues compared with nontumor tissues (all P < 0.01)." (PMID 31990034, 2020). "The combinatorial use of PARP inhibition with E2F8-targeting compounds achieved marked synergy in our GBC models, suggesting that disruption of DNA repair signaling through orthogonal mechanisms may enhance tumor vulnerability." (PMID 41392282, 2025). "This is consistent with our findings that E2F1, but not E2F8 KD induced tumor cell apoptosis." (PMID 38686617, 2024). "Importantly, knockdown of Dbp and E2f8 genes in CD4+ T cell suppresses and promotes Granzyme b, respectively, in Th9 cells in vitro and also in Granzyme B+ T cells in tumor-bearing mice in vivo." (PMID 36241625, 2022). "However, the elevated expression of most of these genes in HCC tumor tissues did not predict patient survival except CDK2 and E2F8, for which a higher expression was associated with poor survival." (PMID 32807134, 2020). "In addition, it showed that IHC scores of E2F8 in tumor tissues were significantly higher than those in normal tissues." (PMID 33224876, 2020). "Most of these genes (STAT5B, CDK6, CDK2, CDKN1B, E2F8, and E2F1) showed high mRNA expression in tumor tissues compared to adjacent non-tumor tissues." (PMID 32807134, 2020). "For example, overexpression of MEX3B in tumors can reduce the lethality of tumor-infiltrating lymphocytes, thereby mediating tumor immunotherapy resistance; NONO promotes cancer proliferation by regulating SKP2 and E2F8, significantly affecting patient prognosis." (PMID 35647031, 2022). "The results showed that the expression levels of E2F2, E2F3, E2F6, and E2F8 are significantly correlated with the tumor stage of PAAD patients, while the expression levels of E2F1, E2F4, E2F5 and E2F7 are not correlated with the tumor stage of PAAD patients." (PMID 33604289, 2020). "As for E2F8, although its role in PAAD has not been reported, our study found that the transcription level of E2F8 in PAAD is significantly higher than in normal tissues, and it is closely related to the tumor stage of PAAD patients." (PMID 33604289, 2020).
cancer (49 papers, 2009 to 2025). A tumor composed of atypical neoplastic, often pleomorphic cells that invade other tissues. "This global approach further highlighted strong correlations between A3B and expression of E2F1, E2F2, E2F7, and E2F8 and indicated that the association between A3B, this signal transduction pathway, and the cell cycle is evident in many cancer types." (PMID 30723127, 2019). "Additionally, E2F8 is one of the E2F family of transcription factors and is crucial for various cellular processes, including those associated with cancer stem cells." (PMID 39061176, 2024). "Furthermore, the PPI interaction network showed 49 coexpressed proteins with E2F8, most of which were cancer-associated proteins." (PMID 36814821, 2023). "E2F8, a novel identified E2F family member, was reported to associate with progression of several human cancers, however, its clinical significance and biological role in PTC remain unknown." (PMID 28270228, 2017). "There is some evidence that E2F8 might also be associated with human cancers." (PMID 31929759, 2020). "Given that E2F8 has been reported to correlate with poor prognosis and chemoresistance in various cancers, we next explored its role in modulating the sensitivity of GBC cells to PARP inhibition." (PMID 41392282, 2025). "It plays a crucial role in cancer by regulating multiple pathways and participating in the E2F8 regulatory network." (PMID 39061176, 2024). "Recent studies reported overexpression of E2F8 in various cancers, suggesting that E2F8 plays an important role in tumorigenesis." (PMID 39021287, 2024). "E2F8 plays a significant role in cancer by affecting the proliferation and differentiation of cancer stem cells (CSCs)." (PMID 39061176, 2024). "The results showed that HOXC13 had a high expression in HER2 cancers and E2F8 had a high expression in basal-like cancers compared with normal tissues." (PMID 36814821, 2023). "E2F8 is a member of the E2F transcription factor family that regulates gene expression required for cell cycle progression, and E2F8 is involved in the development and progression of various cancers." (PMID 37686305, 2023). "The data collectively reveal the opposing activities between DBP and E2F8 in the regulation of Th9 cells in cancer immunotherapy in vivo." (PMID 36241625, 2022). "E2F8 gene, which involves in cell proliferation and cancer development, was found to be highly expressed in C2, C4 and C5 clusters." (PMID 34568003, 2021). "The E2F8 gene has been reported as relevant to CRC as well as in regulating cancer progression and our survival analysis indicates better survival for high E2F8 expression levels." (PMID 34178670, 2021). "E2F8 gene was previously reported highly expressed in several different cancers compared to their normal tissues." (PMID 34568003, 2021). "The newly identified E2F8 has been reported to be an important proliferation factor in some human cancers." (PMID 31929759, 2020). "Particularly, recent literature reported that expression of E2F8 was markedly enhanced in multiple carcinomas, which implies that it is involved in oncogenesis and cancer progression." (PMID 31929759, 2020). "In CRC, E2F8 was highly expressed in cancer tissues and cell lines and a direct target of miR-1258 regulating cell cycle genes." (PMID 33224876, 2020). "The results showed that the mRNA levels of E2F1, E2F2, E2F3, E2F5, E2F7 and E2F8 were significantly lower in adjacent tissues compared with those in carcinoma tissues." (PMID 32117628, 2020). "In accordance with the mRNA expression levels obtained from GEPIA, the protein expression of E2F1, E2F2, E2F3, E2F5, E2F7 and E2F8 were significantly higher in carcinoma tissues." (PMID 32117628, 2020). "E2F transcription factor 1 (E2F1) and E2F transcription factor 8 (E2F8) are upregulated in many cancers and stimulate UHRF1 expression by directly binding to different sites in its promoter region." (PMID 28881702, 2017).
cancer (continued). "Newly identified E2F8 was reported to be a critical proliferation promoter in several human cancers." (PMID 28270228, 2017). "Newly identified E2F8 acts as a potent cell cycle regulator, and has been emerging as a critical proliferation promoter in several human cancers." (PMID 26992224, 2016). "TMPO-AS1 likely sequesters hsa-let-7b-5p, relieving repression of ESPL1 and E2F8, thus, upregulation of hsa-let-7b-5p could disrupt this ceRNA network, attenuating cancer progression by simultaneously targeting oncogenic transcripts and their sponge lncRNA." (PMID 41268575, 2025). "Emerging evidence emphasized the oncogenic role of E2F8 in cancer." (PMID 38605607, 2024). "The study revealed that an increase in a protein called E2F8 and its regulatory networks following BVZ treatment might be associated with the recurrence of cancer." (PMID 39061176, 2024). "Furthermore, we identified key transcription factor regulatory networks regulated by HMGB3, SAP30, and E2F8, which likely played crucial roles in the functional characterization of the cancer stem cell-like B cell subpopulation." (PMID 38149239, 2023). "However, the effects of E2F2, E2F4, E2F6, and E2F8 on prostate etiology and cancer growth are poorly understood." (PMID 37569304, 2023). "Following the upregulation of E2F8, it is hypothesized that its target genes promote the proliferation and differentiation of cancer cells by affecting the RNA translation process." (PMID 37686305, 2023). "The results of downstream target genes in Bulk RNA-seq showed that the activity of translation-related pathways was significantly upregulated after overexpression of E2F8, suggesting that E2F8 promotes cancer cell proliferation and differentiation by affecting the translation process of RNA." (PMID 37686305, 2023). "Notably, DBP and E2F8 also differentially regulate human Th9 differentiation in vitro, suggesting a clinical implication in cancer immunotherapy." (PMID 36241625, 2022). "Single-cell analysis showed that E2F8 may play an important role in tumorigenesis or cancer development." (PMID 33499863, 2021). "Our findings suggest that E2F8 expression correlated with cancer invasion and metastasis." (PMID 31929759, 2020). "Our findings imply that E2F8 expression is correlated with cancer invasion and metastasis." (PMID 32823614, 2020). "The role of the E2F8 gene has been studied in several cancers." (PMID 30832674, 2019). "Therefore, targeting hub genes like E2F8 or multiple targets simultaneously may yield favorable outcomes in cancer treatment." (PMID 39061176, 2024). "The strong effect of the (RB)-E2F pathway in GC progression, along with the cancer-promoting effect of E2F8, agrees with our results, since the observed inhibition of cell cycle progression could be explained in part through the noted downregulation of E2F8 upon GATA KD." (PMID 39456519, 2024). "Moreover, the functional role of E2F8 in cancers is controversial." (PMID 36814821, 2023). "Additionally, we identified the key transcription factor regulatory networks regulated by HMGB3, SAP30, and E2F8 that may play important roles in the functional characterization of the cancer stem cell-like B cell subgroup." (PMID 38149239, 2023). "However, opposite phenomenon of cellular proliferation of E2F8 in human cancers has been reported." (PMID 31990034, 2020). "Hence, the functional effects of E2F8 in human cancers remain obscure." (PMID 31990034, 2020). "Interestingly, recent advances indicated that E2F8 is deregulated in several human cancers." (PMID 26992224, 2016). "Hence, these findings have provided substantial evidence that E2F8 may play a vital role in the malignant progression of cancer." (PMID 26992224, 2016).
cancer (continued). "Proliferative cancer cells specifically express TFs involved in cell proliferation, including E2F TF family members (E2F2, E2F8, and E2F7)." (PMID 37853464, 2023). "Few studies followed E2F8 function in cancer, and so far, no potential E2F8 function in PDAC has been reported." (PMID 38686617, 2024). "The opposing functions of DBP and E2F8, which have been reproduced and confirmed in human TH9 cells, provide potential clinical targets for the development of Th9 cell-mediated immunotherapy for human cancers." (PMID 36241625, 2022). "Indeed, targeting E2F8 has been suggested as a potential therapeutic strategy for cancer treatment; however, there is no small molecule inhibitor of E2F8." (PMID 38605607, 2024).
infection (3 papers, 2022 to 2025). The state of being infected such as from the introduction of a foreign agent such as serum, vaccine, antigenic substance or organism. "Cell cycle arrest was confirmed by the upregulation of p16 (CDKN2A), E2F1 and E2F8 after 24 h post infection with omicron." (PMID 38095608, 2023).